INS (insulin)
Diseases named in the same sentence as INS in open-access papers (continued):
Sharing a sentence is not in itself a finding about the gene and the disease.
type 2 diabetes (continued). "Previous studies have reported the increase of body weight, glucose intolerance, and the levels of serum glucose, serum insulin, serum triglyceride, and free fatty acid in the db/db mice, recapitulating hallmark features of type 2 diabetes." (PMID 35425717, 2022). "The GI of the MED-HEP did not influence changes over time in the fasting risk factors for type 2 diabetes, including fasting glucose, insulin, HOMA-IR, and HbA1c." (PMID 35277067, 2022). "In type 2 diabetes and its pre-clinical manifestations, a loss of insulin sensitivity leads to an exaggerated surge of blood insulin and glucose, following carbohydrate intake." (PMID 35634390, 2022). "Another study suggested that children who consumed breakfast daily had favorable type 2 diabetes risk profiles (i.e., fasting insulin, glucose, and HbA1c), especially in those who consumed high-fiber breakfast cereal." (PMID 35684120, 2022). "In type 2 diabetes, insulin secretion and action deficiency are usually present in the same individual, which is the leading cause of hyperglycemia." (PMID 37746194, 2022). "Most importantly, phenotyping of individuals with prediabetes based on glycemia, abdominal fat distribution, liver fat, IR, and insulin secretion identified sub-populations at greater risk of developing type 2 diabetes and diabetes complications." (PMID 36557310, 2022). "Type 2 diabetes mellitus (T2DM) is chronic metabolic disease caused by defective insulin secretion and/or insulin resistance." (PMID 36242604, 2022). "Most of the pathogenic outcomes of both type 1 and type 2 diabetes are caused by immune-mediated destruction or malfunctioning of insulin-secreting β-cells from the endocrine pancreas and the islets of Langerhans." (PMID 35600869, 2022). "IR refers to a condition in which insulin-responsive cells undergo a reduced response to insulin, caused by disruption of specific events in the signaling pathways resulting in the onset of diseases such as type 2 diabetes." (PMID 36009329, 2022). "In patients with type 2 diabetes studies report an U-shaped association between glycemic control, i.e., HbA1c, and mortality risk especially observed in patients on insulin treatment." (PMID 36435766, 2022). "The SREBF1 gene is associated with obesity, type 2 diabetes and insulin sensitivity, and the gene ABCG1 is involved in cholesterol and phospholipids transport." (PMID 36529747, 2022). "The association between TMAO and Type 2 diabetes was proposed based on multiple mechanisms, including elevated fasting insulin levels and HOMA-IR, aggravating impaired glucose tolerance, and promoting adipose tissue inflammation." (PMID 35631234, 2022). "This is consistent with previous reports that IP3 receptors are upregulated in the β-cells of type 2 diabetics, but associated with impairment of glucose-stimulated insulin secretion and β-cell dysfunction." (PMID 35562179, 2022). "Type 2 diabetes (T2D) accounts for 90–95% of all diabetes cases and is a complex metabolic disorder characterized by insufficient insulin secretion and hyperglycemia caused by insulin resistance (IR)." (PMID 35241134, 2022). "First, we previously analyzed the association between the blood ucOC level and insulin secretion ability in patients with type 2 diabetes." (PMID 35216490, 2022). "Type-II diabetes is the major type in developed countries, often caused by impaired insulin secretion as well as a reduction in the sensitivity of insulin." (PMID 36296720, 2022). "Type 2 diabetes (T2D) is a severe metabolic disease caused primarily by the inadequate production or secretion of insulin." (PMID 36042491, 2022). "The fourth novel SNP, rs4135247, is shared by FIadjBMI and PCOS and is located near PPARG, a gene involved in the insulin signalling pathway in type 2 diabetes that has been found to be associated with PCOS susceptibility." (PMID 35771237, 2022).
type 2 diabetes (continued). "The genome-wide association study of type 2 diabetes (T2DM) in Han Chinese population showed among others that genetic variant near WWOX gene (rs7192960) is associated with reduced insulin secretion." (PMID 35328751, 2022). "The main risk factors for COVID-19 mortality, namely age, obesity, type 2 diabetes and impaired renal function, find a common denominator in leptin and insulin resistance." (PMID 35406000, 2022). "Reduced sensitivity to the action of insulin and deficient insulin secretion are two physiological defects underlying type 2 diabetes (T2D) and impaired glucose tolerance (IGT)." (PMID 36100292, 2022). "An excess of FFA causes a decrease in tissue insulin sensitivity, an increase in glucose levels, and an abnormal lipid profile, leading to dyslipidemia, hypertension, type II diabetes, and inflammation." (PMID 35742405, 2022). "A negative correlation between some aliphatic amino acids was associated with insulin sensitivity and type 2 diabetes." (PMID 35745841, 2022). "This study showed that the risk of insulin initiation was lower in the later years of the study period (2011–2019), which is in line with developing treatment practices of type 2 diabetes." (PMID 36033350, 2022). "Weight-loss effect of non-insulin glucose lowering drugs in patients with type 2 diabetes is also a hot spot of current research." (PMID 36569936, 2022). "In women with type 2 diabetes, larger insulin dose at delivery (in units/kg) associated with longer time for citrate rise, and, by inference, later SA." (PMID 35405936, 2022). "Insulin resistance, a condition associated with reduced cell sensitivity to insulin, predisposes to type 2 diabetes (T2D)." (PMID 35912113, 2022). "Insulin is a major positive regulator of SREBP1c, and the hyperinsulinemia associated with obesity and type 2 diabetes is a risk factor for certain human cancers, including liver and breast cancer." (PMID 36091143, 2022). "Individuals with NAFLD are predisposed toward a deterioration of insulin sensitivity, which results in a two-fold higher incidence of type 2 diabetes mellitus (T2DM)." (PMID 35557545, 2022). "Different from type 2 diabetes (T2D), due to the inefficient use of insulin, T1D is caused by an autoimmune reaction, for which pancreatic β cells are damaged, and insulin cannot be produced." (PMID 36431924, 2022). "We initially focused on the hormones insulin, leptin and adiponectin, as these are known to be directly associated with obesity and are often linked to a type 2 diabetes (T2D)-like phenotype." (PMID 35626717, 2022). "In another clinical study conducted in type 2 diabetes patients, L. eligens was selectively increased by a high dietary fiber diet and negatively associated with postprandial glucose and insulin, body weight, and waist circumference." (PMID 36079886, 2022). "In view of the increasing prevalence of the metabolic syndrome and type II diabetes in the population, further work is required to determine the underlying molecular basis of insulin resistance in the endothelium and the modulatory effects of dietary lipids." (PMID 35157107, 2022). "In the present study, we investigated the association of insulin sensitivity, insulin secretion, and metabolite signature of PA with the risk for type 2 diabetes in a large prospective population-based cohort in Finland." (PMID 35050191, 2022). "While in humans, E4 carriers are at increased risk to develop type 2 diabetes, in the human apoE targeted replacement mice on a high fat diet, fasting glucose and insulin levels were similarly increased in E3 and E4 mice." (PMID 35884888, 2022). "Type 2 diabetes is characterized by chronic hyperglycemia associated with impaired insulin action and secretion." (PMID 35053407, 2022). "Changes in the treatment of type 2 diabetes should be based on the effective inhibition of the loss of insulin-secreting cells, while restoring their full functionality." (PMID 35054822, 2022).
type 2 diabetes (continued). "In type II diabetes; a longer duration of disease and insulin use is associated with an increased risk; (evidence level Ia), which is partly independent of BMD." (PMID 35378630, 2022). "This disturbance is either due to an extreme deficiency in insulin synthesis, which is called type 1 diabetes, or primarily by insulin resistance, which is called type 2 diabetes." (PMID 35335858, 2022). "Type 2 diabetes is characterised by β-cell dysfunction and progressive loss of β-cell insulin secretion, often against a background of insulin resistance." (PMID 35684094, 2022). "Exercise is known to reduce the risk of type 2 diabetes, and daily moderate- or high-intensity exercise is likely optimal to enhance insulin activity." (PMID 35650529, 2022). "Type 2 diabetes is characterized by hyperglycemia that is caused by impaired insulin secretion due to DPP-IV hydrolysis of two incretin hormones, which enhances glucose-induced insulin secretion during meals." (PMID 36496739, 2022). "After restricting to traits thought to be causes of liability to type 2 diabetes, six traits remained: apolipoprotein B, diastolic BP, fasting insulin, hip circumference, total cholesterol and trunk fat percentage (where variable ‘stage2_pad’ is true)." (PMID 35129650, 2022). "In this paper, I studied the risk of insulin initiation in individuals with type 2 diabetes in Finland." (PMID 36033350, 2022). "An impaired insulin-stimulated myocardial glucose metabolism has been shown to be a risk factor for the development of cardiovascular disease in patients with type 2 diabetes." (PMID 35845046, 2022). "The main causes of type-2 diabetes are obesity, insulin resistance, inadequate insulin secretion from β-cells, and inappropriate glucagon secretion." (PMID 36618620, 2022). "Higher predelivery insulin doses in women with type 2 diabetes were associated with increasing time to SA." (PMID 35405936, 2022). "In particular, trivalent chromium is linked with an increase in insulin action and an improvement in glucose tolerance in type 2 diabetes." (PMID 35053903, 2022). "It is known that African Americans are more at risk for type 2 diabetes than European Americans; first-pass hepatic insulin clearance varied from near zero to 45% in that population." (PMID 35163746, 2022). "Insulin increases megalin levels in cell culture under conditions resembling hypertension and type-2 diabetes, both associated with chronic kidney disease." (PMID 36340038, 2022). "The results are consistent with studies which showed that measures of endogenous insulin secretion were inversely associated with the presence of sarcopenia in individuals with type 2 diabetes and that insulin treatment attenuates skeletal muscle mass loss." (PMID 36482911, 2022). "Insensitivity and resistance to insulin are also important pathogenic mechanisms of type 2 diabetes." (PMID 35371260, 2022). "Type 2 diabetes (T2D) is characterized by deficient insulin secretion from pancreatic β‐cells and insulin resistance in peripheral tissues." (PMID 34709731, 2022). "Heterozygous carriers of the rare missense variant T1491.44M of the GLP-1R have a higher risk of type 2 diabetes as result of lower insulin secretion and impaired insulin sensitivity." (PMID 34801547, 2022). "Type 2 diabetes etiology originates not only from the impaired molecular mechanisms of insulin secretion but also from low-grade inflammation causing insulin resistance and promoting β-cell oxidative stress, ER stress, and cell death." (PMID 34180254, 2022). "Impaired secretion of insulin through destruction of the insulin secreting β-cells, and diminished insulin activity through insulin resistance marks the underlying mechanisms of the pathogenesis of type 2 diabetes." (PMID 35282429, 2022). "Type II diabetes is a result of insulin resistance and is more prevalent than type I diabetes, which is caused by insufficient insulin secretion." (PMID 36362847, 2022).
type 2 diabetes (continued). "Although current evidence is mostly negative, it thus remains possible that MI has a minor, but subtle effect on insulin sensitivity and weight, and the long-term effect of MI on the risk of type 2 diabetes in PCOS needs further investigation." (PMID 36557221, 2022). "At the same time, the influence of ARs on the synthesis of serotonin in the intestine, as well as their role in the improvement of sensitivity to insulin and the reduction of the risk of type 2 diabetes development, remains to be elucidated." (PMID 35036005, 2022). "It is characterized by high instability, small changes that can lead to a greatly altered cell response, causing disease such as type 2 diabetes, where the cells become insensitive to insulin." (PMID 36574435, 2022). "Variance in the GCKR locus (glucokinase regulatory gene) has been known to be involved in insulin sensitivity and has been linked to maturity-onset diabetes in young people." (PMID 36458039, 2022). "The subjects were originally recruited based on their genotype at rs7903146 in the TCF7L2 locus where the T (the type 2 diabetes‐associated) allele increased disorderliness of insulin secretion and impaired postprandial suppression of glucagon." (PMID 35822422, 2022). "Vitamin D deficiency has been shown to impair insulin synthesis and secretion in humans and in animal models of diabetes, suggesting a role in the development of type 2 diabetes." (PMID 36358486, 2022). "Previous smaller studies have also reported that choline plasmalogens and lysophosphatidylcholines are associated with a decreased risk of type 2 diabetes, decreased glucose levels, and increased insulin sensitivity." (PMID 35050191, 2022). "In contrast, SAT has been proposed to exert protective roles, as it is associated with glucose tolerance, insulin sensitivity and a low risk for type 2 diabetes after adjustment for BMI." (PMID 36289764, 2022). "On the contrary, F-moHF showed increased circulating levels of ghrelin and GIP compared to F-moC and to M-moHF, which correlates to insulin sensitivity, associated with a reduction of type II diabetes pathway activity." (PMID 36195702, 2022). "Migraine and glucose-related (glycaemic) traits (fasting glucose, fasting insulin, and type 2 diabetes) are common and complex comorbid disorders that cause major economic and social burdens on patients and their families." (PMID 35627115, 2022). "This is currently the only clinical study in which faecal samples of patients were obtained for gut microbiota analysis to unravel the underlying insulin-sensitizing mechanism of the novel DMR procedure for type 2 diabetes." (PMID 36992788, 2022). "The authors used scores composed of variants associated with type 2 diabetes weighted by their genetic effect on measures of insulin secretion and sensitivity." (PMID 35953726, 2022). "GDM results from a reduced capacity for insulin production, and it has been suggested that women who develop GDM have pre-existing defects in insulin action and secretion and are, therefore, predisposed to developing type 2 diabetes." (PMID 34601603, 2022). "We aimed to assess hypoglycemia risk associated with sulphonylurea (SU) and insulin therapy in people living with type 2 diabetes in a low-resource sub-Saharan African setting." (PMID 35450869, 2022). "Muslims with insulin-requiring type 2 diabetes are at high risk of hypo- and hyperglycemia while fasting during the month of Ramadan." (PMID 35634376, 2022). "EGCG effectively facilitated better glycaemic control and insulin susceptibility while at the same time improving the lipid profile and oxidative stress parameters in a rat model of type 2 diabetes." (PMID 35743146, 2022). "One of the causes of type 2 diabetes is oxidative stress, which can induce insulin resistance in peripheral tissues and impair insulin secretion from pancreatic beta cells." (PMID 35742015, 2022).
type 2 diabetes (continued). "Pancreatic β cells are known to secrete insulin to regulate blood glucose and β cell dysfunction causes Type 2 diabetes." (PMID 35614067, 2022). "We propose that impairments in DPP4 control of post-OGTT insulin responses are part of molecular mechanisms underlying early metabolic disturbances associated with type 2 diabetes." (PMID 35190847, 2022). "To examine potential functionality of the main hit we ran several analyses, after annotating the CpG and finding that it maps to the transcription start site of the WNT5B gene, known to be associated with adipogenesis, insulin secretion, and type 2 diabetes." (PMID 35236238, 2022). "Endocrinologists indicated that a resistance to taking insulin therapy can be an important barrier for patients with type 2 diabetes, as there is often an underlying perception of failure and shame when being treated with insulin." (PMID 36175885, 2022). "This study found that in women, patients at an older age, patients with low BMI, and those using insulin or various hypoglycemic drugs, the risk of hypoglycemia developing in type 2 diabetes increases." (PMID 35708754, 2022). "Type II diabetes is mainly caused by insufficient insulin secretion and excessive insulin resistance." (PMID 35343091, 2022). "Vitamin D deficiency is also related to inadequate insulin secretion, altered blood glucose levels, and type 2 diabetes." (PMID 36466412, 2022). "Patients with type 2 diabetes show long-term hyperglycemia, which is caused by insufficient insulin secretion or decreased insulin sensitivity." (PMID 35436905, 2022). "Type 2 diabetes is associated with increased renin angiotensin system flux, which contributes to impaired beta-cell function and reduced insulin sensitivity." (PMID 35733766, 2022). "Type 2 diabetes mellitus (T2DM) is a metabolic disease caused by a relative deficiency of insulin secretion or insulin resistance (IR)." (PMID 36686652, 2022). "KCNJ15, a member of the J subfamily of potassium inward rectifier channels, is mainly expressed in the human kidney and pancreas and is a risk gene for type 2 diabetes; its downregulation promotes insulin secretion." (PMID 36389709, 2022). "Despite poor glucose regulation and high risk for early-onset insulin-deficient type 2 diabetes, they have better kidney function and lower rates of all-cause and cardiovascular-specific mortality compared with people of European ancestry." (PMID 35227251, 2022). "Consistent with our results, other studies also revealed the reduced type 2 diabetes risk among modest drinkers in both Western and Asian populations by improving the insulin sensitivity." (PMID 35523974, 2022). "In this study, we measured fasting C-peptide concentration to assess endogenous insulin secretion and determine the prevalence and characteristics of patients with insulin deficiency in adult Ugandan patients with confirmed type 2 diabetes at presentation." (PMID 36992725, 2022). "Considering that patients with TS are at increased risk of type 2 diabetes and have a specific defect in glucose-stimulated insulin secretion, this is an extremely positive result." (PMID 35907176, 2022). "Identifying patients with new-onset type 2 diabetes who have insulin deficiency can aid in timely insulin replacement therapy." (PMID 36992725, 2022). "Early stages of type 2 diabetes are marked by hyper-insulinemia, while late stages are insulin-deficient which adds complexity to studying this population." (PMID 35596784, 2022). "The imbalance of zinc homeostasis is associated with type 2 diabetes and insulin metabolic disorders." (PMID 35933424, 2022). "Using an unweighted genetic risk score, we examined patterns of associations for the four insulin-related SNVs in relation to development of type 2 diabetes and impaired fasting glucose at follow-up." (PMID 35665752, 2022).